RAMP1 (receptor activity modifying protein 1)
Diseases named in the same sentence as RAMP1 in open-access papers (continued):
Sharing a sentence is not in itself a finding about the gene and the disease.
migraine (continued). "Because it is, to our knowledge, the first time to investigate the methyaltion pattern of RAMP1 in migraine, we could not perform an accurate power calculation." (PMID 26501962, 2015). "But variations in RAMP1 gene have not been found to link with migraine." (PMID 26501962, 2015). "Recently, in a retrospective cohort of 199 migraine patients treated with different anti-CGRP monoclonal antibodies, of which 51.7% of patients were treated with ERE, a nominal association was found between RAMP1 rs12615320 and non-responder status as assessed by the MIDAS question A." (PMID 41464829, 2025). "Results revealed a significant increase in the expression of NPTX-2 and RAMP-1 genes and a significant decrease in the miR-382-5p in the brain tissue of rats with NTG-induced migraines relative to normal rats without migraine induction (p < 0.001)." (PMID 39500819, 2025). "In experimental human studies, activation of AMY1 which expresses RAMP1 but not CLR, can promote migraine in patients with primary headache disorders." (PMID 38658853, 2024). "Clinical trials with anti CGRP or anti RAMP1/CLR monoclonal antibodies, while showing excellent efficacy and safety profile, also indicate that a subset of migraine patients either do not respond or have a partial benefit." (PMID 30764776, 2019).
Hypertension (10 papers, 2014 to 2025). The presence of chronic increased pressure in the systemic arterial system. "Overexpression or knock-in of human RAMP1 in all or solely neural tissues potentiates CGRP-dependent blood pressure reduction in angiotensin II-induced hypertension." (PMID 37483452, 2023). "Numerous in vivo preclinical studies of hypertension and heart failure demonstrated an upregulation of RAMP1 and/or CGRP expression in pathological conditions, indicating a cardioprotective role of CGRP." (PMID 37483452, 2023). "Several in vivo studies of hypertension and heart failure have reported an upregulation of RAMP1 and/or CGRP expression in pathological conditions." (PMID 35283798, 2022). "For instance, in an animal model of Ang II‐induced hypertension, RAMP1 transgenic mice were shown to be protected from increases in their SBP." (PMID 32372557, 2020). "Furthermore, Ang-II is a vasoconstrictor and is known to induce hypertension in human and rodents; however, transgenic expression of human RAMP1 blunts the Ang-II-induced adverse effects of hypertension in mice." (PMID 31312143, 2019). "While much of the literature has focused on identifying predictors of a positive response to CGRP-targeted treatments, our study highlights key factors associated with non-response to ERE, including hypertension, smoking, insomnia treated with medication, and RAMP1 rs6431564 polymorphism." (PMID 41464829, 2025). "This and related knowledge, together with the understanding that global human RAMP1 transgenic mice are protected from hypertension, led us to hypothesize that a stabilized α-CGRP agonist with the ability to remain active over prolonged periods would elicit cardioprotective properties." (PMID 28446517, 2017). "Recent report shows that mice over expressing RAMP1, a co-receptor for AM2 as well as for CGRP, ameliorates ATII mediated hypertension in rodents." (PMID 36875025, 2023). "Mice with augmented expression of RAMP1 (part of the CGRP receptor) have exhibited increased vagal activity and mitigation of angiotensin II-induced hypertension." (PMID 25279791, 2014). "Much like CGRP KO mice, RAMP1 KO mice develop high blood pressure and knock-in or overexpression of human RAMP1 in all or solely neural tissues potentiates CGRP-dependent blood pressure reduction in AngII-induced hypertension." (PMID 35283798, 2022). "Whereas hypertension did not alter RAMP-1 expression (droplet digital (dd) PCR) in either mouse line, RAMP-2 expression dropped significantly in both mouse lines by about 65%." (PMID 25860809, 2015). "Overexpression of RAMP-1 however univocally defines a higher abundance of the CGRP receptors on the cell surface and thus covers the natural hypertension-induced shift in the CGRP / AM sensitivity ratio of the cerebral vasculature that we describe here for the first time." (PMID 25860809, 2015). "Of note, RAMP-1 expression was about 3.5-times higher compared to RAMP-2 expression in the normotensive state in both mouse lines and, more importantly, increased to a 6.6-times higher RAMP-1 expression over that of RAMP-2 due to a significant hypertension-induced drop in RAMP-2 expression." (PMID 25860809, 2015).
melanoma (8 papers, 2018 to 2025). A malignant, usually aggressive tumor composed of atypical, neoplastic melanocytes. "In addition, researchers have used single-cell RNA sequencing analysis to demonstrate RAMP1 overexpression is associated with a poor clinical outcome in patients with melanoma." (PMID 37796823, 2023). "Single-cell RNA-seq revealed that RAMP1-expressing CD8+ T cells exhibited greater exhaustion in melanoma, and the heightened expression of RAMP1 in these CD8+ T cells was linked to a diminished responsiveness to ICB." (PMID 41030446, 2025). "Analysis of single-cell RNA sequencing data from human melanoma samples showed that CD8+ T cells expressing RAMP1 are more likely to be exhausted than RAMP1-negative cells and are associated with a poor prognosis." (PMID 38334648, 2024). "Single-cell RNA sequencing of biopsies from patients with melanoma revealed that intratumoral RAMP1-expressing CD8+ T cells were more exhausted than their RAMP1-negative counterparts, whereas overexpression of RAMP1 correlated with a poorer clinical prognosis." (PMID 36323780, 2022). "B16F10 melanoma cells induce nociceptor neurons to secrete CGRP, which induces exhaustion in receptor activity-modifying protein 1 (RAMP1)-expressing CD8+ T cells." (PMID 41030446, 2025). "Such an expression profile resembles the functional exhaustion of effector CD8+ T cells and suggests that the CGRP receptor RAMP1 influences CD8+ T cell exhaustion and the clinical response to ICI in patients with melanoma." (PMID 36323780, 2022). "In head and neck squamous cell carcinoma (HNSCC) and melanoma, our research has shown that tumor-innervating nociceptors modulate anti-tumor immunity through the release of calcitonin gene-related peptide (CGRP) and its interaction with receptor activity-modifying protein 1 (RAMP1)." (PMID 40951290, 2025).
Ewing sarcoma (7 papers, 2019 to 2025). A small round cell tumor that lacks morphologic, immunohistochemical, and electron microscopic evidence of neuroectodermal differentiation. "Knockdown of RAMP1 reduced clonogenic/spheroidal growth and tumorigenicity, and small-molecule inhibitors directed against the RAMP1 reduced growth of Ewing sarcoma." (PMID 37046795, 2023). "Additionally, targeting the CALCB/RAMP1 axis successfully inhibited tumor growth in a study of Ewing sarcoma." (PMID 37055822, 2023). "In acute myeloid leukemia and Ewing sarcoma, the efficacy of some drugs targeting CGRP and its receptors calcitonin receptor-like receptor (CALCRL) and receptor activity-modifying protein 1 (RAMP1) has been verified." (PMID 37347365, 2023). "In Ewing’s sarcoma (EwS) clonogenic/spheroidal growth and tumorigenicity, RAMP1 (receptor activity modifying protein 1) is a crucial receptor in the assembly of the secretory neuropeptide calcitonin-related polypeptide beta (CALCB)." (PMID 33996533, 2021).
prostate carcinoma (6 papers, 2010 to 2025). A carcinoma that arises from epithelial cells of the prostate gland. "RAMP1 has now also been implicated as a major driver in prostate cancer, and so, linking this to CGRP will hopefully prompt researchers to look at this peptide in more detail." (PMID 28845385, 2017). "It has also been shown that RAMP1 knockdown in prostate cancer cells causes increases in MAPK, ERK1/2 and IL-6." (PMID 28845385, 2017). "However more recently studies associated with RAMP1 may provide evidence of the CGRP receptor promoting prostate cancer and metastasis to the bone." (PMID 28845385, 2017). "In prostate cancer, a recent finding indicates that RAMP1 is a direct target gene of NKX3.1 and serves as a new biomarker." (PMID 40165896, 2025). "Knockdown of RAMP1 in prostate cancer cells blocks the expression of MAP2KI (Dual specificity mitogen-activated protein kinase 1) and p-ERK1/2 (phosphorylated-extracellular signal-regulated kinase 1/2)." (PMID 33996533, 2021). "RAMP1 knockdown in two different prostate cancer cell lines showed decreases in proliferation, colony formation and numbers of cells in S phase of the cell cycle." (PMID 28845385, 2017). "Analysis using Oncomine, a cancer-specific bioinformatics database, found RAMP1 to be significantly upregulated in prostate cancer when compared with other cancers including the breast, bladder, liver, lung and pancreatic (P = 6.36 × 10−47)." (PMID 28845385, 2017). "The receptor activity-modifying protein 1 (RAMP1) could promote tumorigenesis in prostate cancer." (PMID 36059494, 2022). "RAMP1 is an NKX3.1 target gene, upregulated in prostate cancer, and RAMP1 knockdown in prostate cancer cell lines showed a decrease in colony formation, numbers of cells in the S phase, and cell proliferation." (PMID 36980580, 2023).
endometriosis (5 papers, 2019 to 2025). The growth of functional endometrial tissue in anatomic sites outside the uterine body. "Masako Honda“s paper indicated the role of RAMP1 signaling in the regulation of lymphangiogenesis and in the development of endometriosis and provided a promising option for the treatment of endometriosis." (PMID 37143676, 2023). "RAMP1 inhibition with antibodies or small molecule inhibitors is likely to be a useful tool for the treatment of endometriosis." (PMID 32869443, 2020). "Our present data indicate that RAMP1 signalling in both implant host tissues contributes to growth and angiogenesis/lymphangiogenesis in endometriosis." (PMID 32869443, 2020). "In the present study, we have shown in a mouse ectopic endometriosis model that RAMP1 signalling stimulated the growth of implanted endometrial tissue and was a critical regulator of angiogenesis and lymphangiogenesis therein." (PMID 32869443, 2020). "The results suggest that blocking RAMP1 signalling will be a promising strategy for the treatment of endometriosis." (PMID 32869443, 2020). "In conclusion, the accumulation of RAMP1+ macrophages and fibroblasts was the key driver of growth and angiogenesis/lymphangiogenesis in the endometrial tissue implants in a mouse ectopic endometriosis model." (PMID 32869443, 2020). "To elucidate the role of RAMP1 signalling in angiogenesis in endometriosis, we measured the numbers of CD31+ blood vessels in the implants of WT → WT and RAMP1−/− → RAMP1−/− mice." (PMID 32869443, 2020). "The results indicated that the C1 SFRP2+ Fibroblast and C3 RAMP1+ Fibroblast subpopulations predominantly originated from the Endometriosis tissue type, while the C0 FHL2+ Fibroblast and C2 CXCR4+ Fibroblast subpopulations were mostly derived from the Endometriomas tissue type." (PMID 41159025, 2025). "Blockade of RAMP1 is a potential tool for the treatment of endometriosis." (PMID 32869443, 2020). "Thus, immune cells contribute to angiogenesis and the progression of endometriosis via RAMP1 signalling, indicating that neuroimmune interactions play important roles in the pathogenesis of endometriosis." (PMID 32869443, 2020). "Although both accumulated macrophages and fibroblasts in the endometrial tissue implants expressed RAMP1, exactly how and from where these cells are attracted to play a role in endometriosis remains unknown." (PMID 32869443, 2020). "Our results suggest that blocking RAMP1 may be a promising option for the treatment of endometriosis." (PMID 32869443, 2020). "Finally, to confirm the role of CGRP/RAMP1 signalling in endometriosis, we examined the effect of CGRP8‐37 on implant growth, angiogenesis and lymphangiogenesis." (PMID 32869443, 2020). "However, the role of RAMP1 signalling in the regulation of angiogenesis/lymphangiogenesis and in the development of endometriosis remains unknown." (PMID 32869443, 2020). "The similarity in CGRP levels in the DRG and in the CGRP+ innervation of implants in the WT → WT and RAMP1−/− → RAMP1−/− mice demonstrates that RAMP1 signalling is crucial for the development and maintenance of endometriosis." (PMID 32869443, 2020). "More remarkably, lesional nerve fiber density correlated with the lesional expression levels of NK1R, RAMP-1 and CRLR, and ultimately with the extent of lesional fibrosis as well as the severity of pain in women with endometriosis." (PMID 30804432, 2019). "Regarding tissue type preference, the C0 FHL2+ Fibroblast and C2 CXCR4+ Fibroblast subpopulations were more common in Endometriomas, while the C3 RAMP1+ Fibroblast, C1 SFRP2+ Fibroblast, and C4 TFF3+ Fibroblast subpopulations were predominantly found in Endometriosis." (PMID 41159025, 2025). "Further studies will be needed to clarify whether blockade of RAMP1 signalling rescues patients with endometriosis from chronic pelvic pain and to investigate whether the CGRP/RAMP1 axis offers new potential therapeutic targets for the treatment of endometriosis." (PMID 32869443, 2020).
endometriosis (continued). "Since the expression of RAMP-1 and CRLR, the two receptors for CGRP, has not been reported in endometrium or endometriosis, we also stained the two for normal endometrial tissues." (PMID 30804432, 2019).
Headache (4 papers, 2019 to 2025). Cephalgia, or pain sensed in various parts of the head, not confined to the area of distribution of any nerve. "Together, the findings suggest that Schwann cell CLR/RAMP1 mediates the CGRP-dependent component of PMA in a mouse headache model." (PMID 35115501, 2022). "CLR/RAMP1, or CGRP receptor, antagonists have been developed for thetreatment of migraine headache and osteoarthritis pain; whereas CLR/RAMP2, orADM receptor, antagonists are being developed for the treatment of tumorgrowth/metastasis." (PMID 31150417, 2019). "With this being said, the pathogenesis of migraine headaches and PTH do have fundamental differences that may have contributed to a presumed link between CALCA gene and RAMP1 locus in the data presented herein, but not in the study of adult migraineurs." (PMID 35989941, 2022).
oral cancer (4 papers, 2023 to 2025). "High expression of RAMP1 was also confirmed in cultured oral cancer cells and orthotopic xenografts, contributing to oral cancer pain." (PMID 38334648, 2024). "Multiple cells within the oral cancer microenvironment expressed the CGRP receptor (CLR/RAMP1), with the percentages of cells being greater in fibroblasts and immune cells." (PMID 37443709, 2023). "Expression of RAMP1 in oral cancer cell lines was higher in cancer cell lines than in the dysplastic cell line, DOK and expression was higher in the cancer cell lines and DOK than in HaCaT, a spontaneously immortalized non-tumorigenic skin cell line." (PMID 37443709, 2023). "YAP1 is an overexpressed and amplified oral cancer oncogene, suggesting a role for RAMP1 in oral cancer promotion." (PMID 37443709, 2023). "Additionally, receptor activity-modifying protein 1 (RAMP1), a key component of CGRP receptors, overexpressed in oral cancer cells, may potentially be associated with the promotion of oral cancer." (PMID 39906323, 2024). "In both HSC-3 and OSC-20 xenografts, fibroblasts and immune cells were enriched for the Ramp1 + Calcrl cells, suggesting that CGRP in the oral cancer microenvironment is likely to impact the functions of these cell types." (PMID 37443709, 2023).
osteosarcoma (4 papers, 2023 to 2025). A usually aggressive malignant bone-forming mesenchymal neoplasm, predominantly affecting adolescents and young adults. "Although there were no available antibodies to TAC4, the protein expression of MYC, P4HA1, and RAMP1 was found to be significantly higher in osteosarcoma tissues than in normal tissues." (PMID 37055822, 2023). "RAMP1 was mainly expressed in malignant tumor cells, especially in chondroblastic osteosarcoma cells." (PMID 37055822, 2023). "The effect of RAMP1 on the malignant phenotype of osteosarcoma cells was cell type dependent." (PMID 37055822, 2023). "Receptor activity modifying protein 1 (RAMP1) facilitates the localization of the calcitonin-like receptor (CLR) to the plasma membrane, but its role in osteosarcoma (OS) remains unclear." (PMID 37796823, 2023). "In addition, in the independent validation cohort, it was found that osteosarcoma patients with high MYC, P4HA1, and RAMP1 protein expression had worse RFS." (PMID 37055822, 2023).
Photophobia (4 papers, 2015 to 2023). Excessive sensitivity to light with the sensation of discomfort or pain in the eyes due to exposure to bright light. "Furthermore, due to animal experiments revealing a link between overexpression of hu-RAMP1 and photophobia, we are sought to discover the differences of methylation pattern." (PMID 26501962, 2015).
asthma (3 papers, 2014 to 2025). "We found that the expression of RAMP1 was associated with the severity of asthma." (PMID 26302899, 2015). "We found that RAMP1, FSCN1, PSTG1 and SPINT2 genes could be associated with the development of severity of asthma." (PMID 26302899, 2015). "Since drug compounds can be developed to specifically target RAMP-receptor interfaces, compounds targeting the CLR/RAMP1 interface may be useful in providing relief from asthma." (PMID 25010197, 2014). "Finally, since RAMP-receptor interfaces are pharmacologically tractable, it may be possible to develop compounds targeting the RAMP1/CLR interface to assist in the treatment of asthma." (PMID 25010197, 2014). "To investigate the protective role of CGRP–RAMP1 signaling in allergic asthma, we first examined WT, Ramp1−/− and Calca−/− mice in an HDM-induced asthma model." (PMID 41472747, 2025). "Together, these data indicate that signaling through RAMP1 and CLR plays a role in mediating asthma pathology." (PMID 25010197, 2014). "RAMP1 is known to interact with CLR to form a receptor for CGRP, indicating that aberrant CGRP signaling may contribute to the pathology of asthma." (PMID 25010197, 2014). "Since RAMP1 and CLR interact to form a receptor for CGRP, our data indicate that aberrant CGRP signaling, perhaps on lung endothelial and inflammatory cells, contributes to asthma pathophysiology." (PMID 25010197, 2014).
colitis (3 papers, 2018 to 2025). Inflammation of the colon. "Previously, we reported that RAMP1 is expressed by T cells, dendritic cells, and macrophages, and that RAMP1 expression by these immune cells is essential for development of inflammation during endotoxemia and colitis." (PMID 30462657, 2018). "As it relates to the colon, in animals with DSS‐induced colitis, only the expression of TRPV1 and Ramp1, on experimental Day 35, was affected, with a significant up‐regulation (both p < 0.05 vs. control)." (PMID 36239298, 2022). "Within the lumbosacral spinal cord, an overall up‐regulation of anti‐nociceptive‐related markers (p < 0.05 for CB1, CB2, and MOR vs. control) and a down‐regulation of pro‐nociceptive‐related markers (p < 0.05 for TRPV1 and 3 and Ramp1 vs. control) was detected following DSS‐induced colitis." (PMID 36239298, 2022).